CHADL (chondroadherin like)
Description:
Potential negative modulator of chondrocyte differentiation. Inhibits collagen fibrillogenesis in vitro. May influence chondrocyte's differentiation by acting on its cellular collagenous microenvironment.
Synonyms: SLRR4B
Tractability: Small molecule: it belongs to a druggable protein family. Antibody: UniProt places it where antibodies can reach, with high confidence; its Gene Ontology location is reachable by antibodies, with high confidence; UniProt predicts a signal peptide or a membrane-spanning region.
Gene: Protein-coding gene on chromosome 22 (41,229,510 to 41,240,931, reverse strand). Ensembl gene ENSG00000100399.
Subcellular location: Secreted; Secreted, extracellular space, extracellular matrix
Gene Ontology:
Molecular function: collagen binding; collagen fibril binding; extracellular matrix structural constituent conferring compression resistance; signaling receptor activity
Biological process: negative regulation of collagen fibril organization; negative regulation of chondrocyte differentiation
Cellular component: extracellular region; gel phase of interstitial matrix; extracellular matrix
Genetic constraint (gnomAD): Loss-of-function variants: 48 observed, 43.15 expected, observed/expected ratio (o/e) 1.11, 90% interval 0.88 to 1.41. The upper end of that interval is the gene's LOEUF score, 1.41, which puts it in group 5 of 6, group 1 being the genes least tolerant of losing a copy. Missense variants: 977 observed, 910.36 expected, observed/expected ratio (o/e) 1.07, 90% interval 1.02 to 1.13. Synonymous variants: 498 observed, 441.69 expected, observed/expected ratio (o/e) 1.13, 90% interval 1.05 to 1.21.
Homologues: Orthologues: chimpanzee CHADL (99% identical), macaque CHADL (94% identical), rabbit CHADL (84% identical), mouse Chadl (81% identical), rat Chadl (80% identical), pig CHADL (79% identical), guinea pig CHADL (74% identical), Caenorhabditis elegans sma-10 (17% identical), Drosophila melanogaster CG7509 (14% identical), Drosophila melanogaster CG18095 (13% identical), Drosophila melanogaster Con (13% identical), Drosophila melanogaster kek3 (13% identical), and 3 more. Paralogues in human: CHAD (19% identical), LRIG1 (19% identical), TRIL (19% identical), CPN2 (19% identical), LRIG3 (17% identical), LRIG2 (17% identical), LGR4 (16% identical), LGR6 (16% identical), LGR5 (15% identical), LRRTM2 (15% identical), LRG1 (13% identical), LRRC24 (13% identical), and 10 more.
Diseases named in the same sentence as CHADL in open-access papers:
CHADL is named in the same sentence as 1 disease in open-access papers, as found by Europe PMC text mining. Sharing a sentence is not in itself a finding about the gene and the disease. The quoted sentences say what the papers report.
cartilage disease (1 paper, 2020). Softening and degeneration of the CARTILAGE. "An important CHAD paralog is CHADL, which can negatively regulate chondrocyte differentiation, inhibiting cartilage fibrillogenesis and can be used as a marker for cartilage diseases." (PMID 32493207, 2020).